CTLA4 (cytotoxic T-lymphocyte associated protein 4)
Diseases named in the same sentence as CTLA4 in open-access papers (continued):
Sharing a sentence is not in itself a finding about the gene and the disease.
tumor (continued). "Furthermore, we investigated 22 key immune checkpoint modulators in HCC, since these co-stimulatory or inhibitory modulators, especially CTLA-4, PD-1, or PD-L1, may sustain or restrict the anti-tumoral potency of tumor-associated T cells." (PMID 33552954, 2020). "FUS-BBB opening could enhance delivery of immune-stimulating agents such as interleukin-12 (IL-12) or immune check point inhibitors such as anti-cytotoxic T-lymphocyte-associated antigen 4 (CTLA-4) monoclonal antibodies (mAb) to affect the tumor immunosuppressive microenvironment." (PMID 30792657, 2019). "The gut microbiome has been shown to modulate the anti-tumor efficacy in pre-clinical models of various chemotherapies and immunotherapeutic agents, including antibodies against cytotoxic T lymphocyte-associated antigen 4 (CTLA4) and anti-programmed cell death protein 1 (PD-1)." (PMID 31316514, 2019). "Therefore, PD-1/PD-L1 signaling is more specific to tumor than CTLA-4 signaling, and inhibitors of PD-1/PD-L1 may cause less damage to healthy tissue." (PMID 30774597, 2019). "Tumor immune evasion is a fundamental hallmark of cancer cells, facilitated by T-cell “checkpoint” receptors such as cytotoxic T-lymphocyte-associated antigen-4 (CTLA-4) and programmed cell death protein-1 (PD-1) and is an important area of scientific investigation and interest." (PMID 30654522, 2019). "In detail, cytotoxic T-lymphocyte-associated antigen 4 (CTLA-4)/B7-1 or B7-2 and programed cell death 1 (PD-1)/its ligands programed cell death 1 ligand 1 (PD-L1) or PD-L2 axis are recognized to be the most important central checkpoints in the immune invasion for tumor progression." (PMID 30884772, 2019). "Furthermore, α-TGFβ or α-PD-1 monotherapy elevated the percentage of CD8+ T cells that express markers of late T cell differentiation and partial T cell exhaustion, ICOS and CTLA4, that have also been associated with active anti-tumor responses in human tumors." (PMID 30832732, 2019). "Moreover, for some low PD-L1 expression patients, α-CTLA-4 might decrease the risk of resistance to α-PD-1 and demonstrate the synergistic anti-tumor effect." (PMID 31673481, 2019). "In particular, tumor-infiltrating immune cells, analysis of gene expression, mismatch-repair deficiency, and/or tumor mutational landscape may play an important role in predicting clinical benefits of CTLA-4 and PD-1/PD-L1 checkpoint inhibitors." (PMID 31179334, 2019). "A recent analysis of whole-exome sequencing data of 110 pretreatment melanoma tumor biopsies with matching germline tissue samples and RNA-seq data from a subset of 42 patients revealed that a lower burden of copy number loss was significantly associated with clinical benefit to CTLA-4 blockade." (PMID 31658667, 2019). "Escape mechanisms include down-regulation of tumor antigens, alterations of target antigens by alternative splicing, activation of alternative signaling pathways, and overexpression of inhibitory signals (e.g., cytotoxic T-lymphocyte-associated antigen 4 (CTLA4) or programmed cell death-1 (PD1))." (PMID 31109083, 2019). "A hallmark of tumor-associated T cells is a state of hyporesponsiveness or functional exhaustion, marked by persistent expression of surface inhibitory markers including PD-1, CTLA4, LAG3, TIM3 and others, many of which are expressed following T cell activation." (PMID 31624246, 2019). "Programmed Death 1 (PD-1) and Cytotoxic T-lymphocyte Associated Protein 4 (CTLA-4) are immune-inhibitory receptors (immune checkpoints) expressed mainly on T cells, and their inhibition with function-blocking antibodies has been shown to enhance anti-tumor T cell responses." (PMID 31824260, 2019). "In particular, tumor-infiltrating immune cells, gene expression analysis, mismatch- repair deficiency, and tumor mutational landscape may play a central role in predicting clinical benefits of CTLA-4 and/or PD-1/PD-L1 checkpoint inhibitors." (PMID 31179334, 2019).
tumor (continued). "Collectively, these findings support the hypothesis that the inhibition of IDO1 may increase intratumoral inflammation and increase tumor susceptibility to checkpoint inhibition, making it an ideal target for combining with the inhibition of PD-1 and/or CTLA-4." (PMID 29805749, 2018). "However, all anti-CTLA-4 antibodies caused robust tumor rejection in CTLA4h/m mice." (PMID 29713453, 2018). "In addition, several researchers documented the increased immunological anti-tumor effect in combination with dendritic cells as well as several immune-regulatory agents including lipopolysaccharide and anti-cytotoxic T lymphocyte-associated antigen 4 (CTLA-4) antibody." (PMID 28592286, 2017). "The susceptibility of tumors to regress with CTLA-4 blockade was further shown to correlate with the immunogenicity of the tumor, and the response in poorly immunogenic tumors could be augmented by co-treatment with granulocyte-macrophage colony-stimulating factor (GM-CSF) vaccines." (PMID 29211042, 2017). "Indeed, new anti-cancer therapies, such as ipilimumab which is a blocking antibody to cytotoxic T lymphocyte-associated protein-4 (CTLA-4), are associated with increased infiltration of T lymphocytes into the tumor tissue and significantly increased survival rates." (PMID 29020986, 2017). "The mechanism underlying the clinical activity of CTLA-4 immunotherapy is currently under investigation, and recent experimental findings indicate that antibody-mediated depletion of regulatory T cells (Tregs) in the tumor microenvironment plays a key role in efficacious antitumor responses." (PMID 25973756, 2015). "This tumor regression was associated with antibody responses against a tumor-specific cancer testis antigen, suggesting that augmentation of tumor-specific immune responses had occurred and demonstrating the promise of a combination of radiotherapy and CTLA-4 blockade in a clinical setting." (PMID 24686897, 2014). "Thus, it is hypothesized that in cancer disease antitumor responses such as proliferation and activation of tumor-specific CTLs may also be altered by genetic polymorphisms in CTLA-4 gene." (PMID 23936819, 2013). "In murine models, while curcumin, anti-PD-L1, or anti-CTLA4 monotherapy significantly reduced tumor growth rates, combination treatments further decreased tumor growth rates, volumes, and weights." (PMID 41522360, 2026). "Cebpb overexpression promoted tumor growth in the immunocompetent syngeneic mouse models, which was accompanied by increased CTLA-4 expression in tumor-infiltrating CD4+ T cells." (PMID 41743630, 2026). "Before challenge with tumor cells, the expression of exhaustion-associated surface markers—including PD-1, TIM-3, LAG-3, TIGIT, and CTLA-4—was comparably low between iCD4+ and iCD8+ T cells." (PMID 41484912, 2026). "Research indicates that Candida albicans can promote the activation and recruitment of CD4+ T cells and CD8+ T cells to tumor sites by modulating the CTLA‐4 signaling pathway." (PMID 41574027, 2026). "In the tumor microenvironment, the silencing of immune checkpoints like PD-1 and CTLA-4 has demonstrated the ability to restore T cell function and enhance the efficacy of adoptive cell therapies." (PMID 41750383, 2026). "Mouse study showed that the tumor suppressive effect of CTLA-4 depletion in allograft cancer models via senescence induction." (PMID 41639053, 2026). "These compounds were validated in molecular and cellular assays and had demonstrated significant tumor growth inhibition in CTLA-4 humanized tumor-bearing mice." (PMID 41486149, 2026). "The emergence of immune checkpoint inhibitors (ICIs), specifically targeting PD-1/PD-L1 and CTLA-4 pathways, has revolutionized the treatment landscape by restoring anti-tumor immune responses." (PMID 42088497, 2026). "In vitro co-culture experiments also showed that tumor cell CEBPB overexpression increased CTLA4 in T cells." (PMID 41743630, 2026).
tumor (continued). "When incorporated into a CAR construct, CleTAC targeting CTLA4 enhanced CAR-T cell anti-tumor activity, as evidenced by improved functional assays and tumor suppression in animal models." (PMID 41328344, 2026). "Subsequently, it induced an antitumor immune microenvironment, promoted the Th1 type helper T‐cell immune response, and the maturation of DCs within the tumor, thereby significantly enhancing the treatment response of mice to the CTLA‐4 antibody." (PMID 41574027, 2026). "In contrast, CTLA-4+ Tregs were significantly enriched in tumor-infiltrating Tregs compared to PBMC-derived Tregs." (PMID 41399390, 2026). "Further analyses showed that the combination treatment elevated PD-1, LAG3, TIM-3, and CTLA-4 expression in bulk tumor samples, a pattern most consistent with increased T-cell infiltration and activation." (PMID 41484455, 2026). "TGF‐β blockade markedly suppressed the growth of HBx‐overexpressing tumours, whereas PD‐1/CTLA‐4 dual blockade exerted only modest effects." (PMID 41492119, 2026). "T cell-intrinsic VISTA deficiency cooperated with CTLA-4 blockade to improve T cell survival and broaden TCR repertoire diversity, resulting in more robust tumor regression than CTLA-4 inhibition alone." (PMID 41837284, 2026). "For instance, scientists have modified Lactococcus lactis to produce both anti-PD-L1 nanobodies and anti-CTLA-4 antibodies, resulting in a strong synergistic effect that significantly enhanced tumor suppression in breast cancer animal models." (PMID 41355950, 2026). "Tumor cells utilize various mechanisms to evade immune system surveillance, including the expression of checkpoint proteins such as PD-L1, CTLA-4, Galectin-9, and PVR." (PMID 41550509, 2026). "By modulating the microbiome and enhancing anti-tumor immunity, probiotics can improve the response to ICIs such as anti-PD-1 or anti-CTLA-4 antibodies." (PMID 41355950, 2026). "This mechanistic insight directly explained why TGF‐β blockade achieved superior anti‐tumour efficacy compared with PD‐1/CTLA‐4 inhibition in our in vivo model, highlighting the translational potential of targeting this pathway in GCB‐DLBCL." (PMID 41492119, 2026). "In this study, we propose integrating CME-based targeted degradation into CAR-T cell therapy to optimize anti-tumour efficacy by reducing CTLA4 expression." (PMID 41328344, 2026). "ICBs inhibit cytotoxic T-lymphocyte antigen 4 (CTLA-4), programmed death 1 (PD-1), and PD-1 ligand 1 (PD-L1), which inhibit antitumor immune responses in the tumor microenvironment, and promote antitumor efficacy." (PMID 40768094, 2026). "Changes in these genes can control how the tumour interacts with the immune system and influence the expression of immune checkpoint molecules such as PD-1, PD-L1, PD-L2, CTLA-4 and CD47." (PMID 41834250, 2026). "When combined with anti-PD-1 and anti-CTLA-4 therapies, rAd.sT further reduced tumor volume suppressed metastatic nodules, and showed potential for reprogramming the TME." (PMID 40281554, 2025). "Immune checkpoint inhibitors (ICIs) have redefined cancer therapy by blocking pathways such as PD-1/PD-L1 and CTLA-4, thereby restoring antitumor immunity and altering the tumor microenvironment (TME)." (PMID 40940902, 2025). "The blockade of CTLA-4's suppressive function allows and enhances the effective immune response against tumor cells." (PMID 40861801, 2025). "On the other hand, a CTLA-4 inhibitor (clone 9D9) in combination with anti-PD-1 antibody and cisplatin inhibited tumor growth in a mouse model of cholangiocarcinoma." (PMID 39757995, 2025). "Immune checkpoint inhibitors such as PD-1/PD-L1 and CTLA-4 antibodies reactivate the body’s anti-tumor immune response by relieving tumor cell suppression of the immune system." (PMID 40766320, 2025).
tumor (continued). "For example, Bifidobacterium-derived inosine improves anti-CTLA-4 treatment efficacy in colorectal cancer, whereas in hepatocellular carcinoma, microbial metabolites such as fatty acids promote tumor progression via direct interactions with tumor cells." (PMID 41326352, 2025). "The higher expression of CD274 and CTLA4 in low-risk patients suggests that they may benefit more from immune checkpoint inhibitors, as these molecules help regulate immune response and prevent the release of excessive pro-inflammatory cytokines, thereby potentially limiting tumor progression." (PMID 40103813, 2025). "Since the increase of TA-HEVs relies on Fc-dependent mechanisms during anti-CTLA-4 therapy, we next examined how an Fc-enhanced version of 9D9 (mouse IgG2a Fc) would modulate tumor-infiltrating CD4+ T cells and TA-HEVs." (PMID 40460830, 2025). "Immune checkpoint inhibitors, particularly those targeting CTLA-4 and PD-1/PD-L1 pathways, play a crucial role in counteracting tumor immune evasion mechanisms." (PMID 40904451, 2025). "Our immunohistochemistry studies confirmed that PD-L1 is expressed both in tumor and infiltrating cells, while CTLA-4, PD-1, PD-L1, TIM-3, TIGIT, and VISTA were identified in infiltrating cells, both intratumorally and peritumorally." (PMID 40565313, 2025). "Agents such as anti-CD25 antibodies and CTLA-4 inhibitors are being explored for their potential to reduce Treg-mediated immunosuppression and restore effective anti-tumor responses." (PMID 40170852, 2025). "Conversely, low levels of CTLA-4+ tumor-infiltrating lymphocytes (TILs) were significantly associated with a more advanced tumor stage and a higher number of positive LNs." (PMID 40149674, 2025). "Key advancements include the integration of immune checkpoint inhibitors (ICIs) like PD-1/PD-L1 and CTLA-4 inhibitors into clinical practice and the development of bispecific antibodies and ADCs targeting tumor-specific antigens like glypican-3." (PMID 40621467, 2025). "Depletion of MNX1 stimulates T cell anti‐tumor immunity, inhibits tumor progression, and sensitizes CTLA‐4 blockade therapy." (PMID 39912421, 2025). "Distributions of quantitative whole tumour PD‐L1, PD‐1 and CTLA‐4 in situ RNAscope expression with respect to the grade of tumour infiltrating lymphocytes (TILs) (Wilcoxon's rank‐sum test)." (PMID 39789732, 2025). "In patients, tumor-infiltrating T cells commonly express high levels of immune checkpoints (e.g., PD-1, CTLA-4) and reduced cytotoxic mediators, indicating functional exhaustion." (PMID 41583439, 2025). "CTLA-4 inhibition revitalizes anti-tumor immunity by interrupting the B7–CD28 costimulatory axis and promoting the depletion of immunosuppressive regulatory T cells." (PMID 41244900, 2025). "Cadonilimab, a BsAb that targets PD-1 and CTLA-4, regulates T-cell activity to boost anti-tumor immune responses." (PMID 41239350, 2025). "Tumor lactate enhances Treg CTLA4 stability (doubling its half-life), exacerbating immunosuppression." (PMID 41415289, 2025). "Immune checkpoint inhibitors, such as anti-PD-1 and anti-CTLA-4 antibodies, enhance the immune system's ability to target tumor cells." (PMID 40584522, 2025). "While CTLA-4 has been primarily studied for its role in regulating anti-tumor immune responses, emerging studies have begun to shed light on its potential role in CSCs." (PMID 41233805, 2025). "Fourth, PIEZO1 shows positive associations with tumor microenvironment scores (Stromal/Immune/ESTIMATE) and immune checkpoint markers (CD274, CTLA4, LAG3, PDCD1, PDCD1LG2)." (PMID 40977743, 2025). "Studies have shown that ipilimumab, an antibody against CTLA-4, is able to reduce the number of Treg through FcγR-mediated effects, thereby enhancing the activity of anti-tumor T cells." (PMID 40385461, 2025). "Trials combining nanoparticle-delivered OX40 agonists (CD4+ T-cell costimulators) with anti-CTLA-4 antibodies show improved tumor regression in advanced cancers." (PMID 40860882, 2025).
tumor (continued). "Cytotoxic T lymphocytes (CTLs) play a key role in tumor surveillance, but their activity can be suppressed by immune checkpoints such as CTLA-4, which inhibits early T cell activation by binding to B7 molecules on antigen-presenting cells." (PMID 40943370, 2025). "Inhibition of CTLA-4 has been shown to restore T cell activity and enhance tumor cell recognition and destruction, thus impeding tumor progression and metastasis." (PMID 40808954, 2025). "Due to the significant clinical efficacy of PD‐1 and CTLA‐4 inhibitors, as well as their broad applicability across various tumor types, this review will primarily focus on discussing these two classes of drugs." (PMID 40900811, 2025). "We demonstrate that the antibody Fc effector function and CD4+ T cells are both required for the remodeling of tumor blood vessels and the increase of TA-HEVs during anti-CTLA-4 therapy." (PMID 40460830, 2025). "In the comparison between chemo and chemo > α-PD-1 + α-CTLA-4 groups, we observed differentially expressed pathways including multiple metabolism pathways and tumor-stroma interacting pathways." (PMID 39871312, 2025). "CTLA-4 inhibitors competitively bind to ligand B7 with CTLA-4, relieving the inhibitory factors that impede T cell activation, thereby exerting an anti-tumor effect." (PMID 41256848, 2025). "Ipilimumab enhances T cell activation and proliferation by blocking the interaction between CTLA-4 and B7 molecules on antigen-presenting cells, thereby exerting its anti-tumor effects." (PMID 40260303, 2025). "Another approach involves combining anti-CTLA-4 with DC-derived EVs, resulting in enhanced T cell responses and the inhibition of tumor-draining lymph node growth." (PMID 40006624, 2025). "CD4+ naive/central-memory T cells from tdLN directly respond to anti-cytotoxic T lymphocyte antigen-4 (anti-CTLA4) therapy, trafficking via blood to the tumor, where they acquire a Th1 phenotype." (PMID 41030446, 2025). "Both PD-1/PD-L1 and CTLA-4 are pivotal in modulating T cell responses within the tumor microenvironment." (PMID 40565041, 2025). "This is explained by the early and systemic T-cell activation resulting from CTLA-4 neutralization, whereas the PD-1/PD-L1 pathway modulates a more restricted T-cell activation within the tumor microenvironment." (PMID 40305184, 2025). "JG-1 exhibited potent tumor growth inhibition across multiple syngeneic models and demonstrated synergistic effects when combined with anti-CTLA-4 antibody therapy." (PMID 39325360, 2025). "Specifically, ICIs targeting CTLA-4 and PD-1/PD-L1 have become the focal point of recent tumor immunotherapy research." (PMID 40012016, 2025). "This leads to upregulation of PD-1, PD-L1, and CTLA-4 expression, which adversely affects anti-tumor immunity and represents a key factor in the development of HPD." (PMID 40575167, 2025). "The combination of anti-PD-1 and anti-CTLA-4 blockade has proven the possibility of strengthening the anti-tumor response by acting via two separate mechanisms." (PMID 40362333, 2025). "Tumor biopsies at day 8 or 28 taken from 14/24 patients showed an increased CD8+ T‐cell infiltration, reduced Tregs, and upregulation of immune checkpoints like PD‐1 and CTLA‐4 in approximately 50% of the tumor biopsies." (PMID 40726054, 2025). "The amplitude ratio of free NADH to protein‐bound NAD(P)H was significantly higher for immunotherapy responders (anti‐CTLA‐4‐therapy, multiple treatments) compared to non‐responders and an untreated tumour control group." (PMID 40112892, 2025). "Immune checkpoint drugs, primarily targeting CTLA-4, PD-1, and PD-L1, empower T cells to eliminate tumor cells." (PMID 40136857, 2025). "PD-L1 expression in tumor cells and immune cells, as well as CTLA-4+ tumor-infiltrating lymphocytes, informs response to checkpoint inhibitors." (PMID 40941632, 2025). "In vivo depletion of eosinophils abrogated the effect of anti-CTLA4 therapy on tumor vessel normalization and dampened its therapeutic efficacy." (PMID 40050933, 2025).